FAHD2A (fumarylacetoacetate hydrolase domain containing 2A)
Description:
Tautomerase that converts enol-oxaloacetate, a strong inhibitor of succinate dehydrogenase, to the physiological keto form of oxaloacetate. It is thereby required to maximize aerobic respiration efficiency by preventing succinate dehydrogenase inhibition.
Synonyms: CGI-105
Tractability: PROTAC: ubiquitination databases record sites on it; its protein half-life has been measured.
Gene: Protein-coding gene on chromosome 2 (95,402,691 to 95,416,616, forward strand). Ensembl gene ENSG00000115042.
Subcellular location: Mitochondrion
Gene Ontology:
Molecular function: oxaloacetate tautomerase activity; protein binding; catalytic activity
Biological process: oxaloacetate metabolic process
Cellular component: mitochondrion
Genetic constraint (gnomAD): Loss-of-function variants: 27 observed, 35.3 expected, observed/expected ratio (o/e) 0.76, 90% interval 0.56 to 1.05. The upper end of that interval is the gene's LOEUF score, 1.05, which puts it in group 4 of 6, group 1 being the genes least tolerant of losing a copy. Missense variants: 296 observed, 400.68 expected, observed/expected ratio (o/e) 0.74, 90% interval 0.67 to 0.81. Synonymous variants: 130 observed, 151.1 expected, observed/expected ratio (o/e) 0.86, 90% interval 0.75 to 1.
Homologues: Orthologues: chimpanzee FAHD2A (99% identical), macaque FAHD2A (98% identical), dog FAHD2A (94% identical), rabbit FAHD2A (90% identical), guinea pig FAHD2A (89% identical), mouse Fahd2a (86% identical), rat Fahd2a (84% identical), tropical clawed frog fahd2a (67% identical). Paralogues in human: FAHD2B (98% identical), FAH (26% identical), FAHD1 (26% identical).
Diseases named in the same sentence as FAHD2A in open-access papers:
FAHD2A is named in the same sentence as 1 disease in open-access papers, as found by Europe PMC text mining. Sharing a sentence is not in itself a finding about the gene and the disease. The quoted sentences say what the papers report.
Obesity (1 paper, 2024). Accumulation of substantial excess body fat. "In the present study, we have identified four differentially expressed genes shared between obesity and HCC, namely ESR1, GCDH, FAHD2A, and DCXR." (PMID 38977823, 2024). "Four differentially expressed genes, including ESR1, GCDH, FAHD2A, and DCXR, were found to overlap between HCC and obesity." (PMID 38977823, 2024). "Four differentially expressed genes (ESR1, GCDH, FAHD2A, DCXR) were common in obesity and HCC." (PMID 38977823, 2024).